ERAP1 (endoplasmic reticulum aminopeptidase 1)
Diseases named in the same sentence as ERAP1 in open-access papers (continued):
Sharing a sentence is not in itself a finding about the gene and the disease.
cervical carcinoma (continued). "Allele distribution patterns in Bali and Java differed in relation to cervical carcinoma risk, with four ERAP1 SNPs and one TAP2 SNP in the Javanese population showing significant association with cervical carcinoma risk, while in the Balinese population, only one TAP2 SNP showed this association." (PMID 25796583, 2015). "Moreover, genetic variation in the ERAP1 gene is associated with both increased cervical carcinoma risk and decreased survival among patients." (PMID 26146606, 2015). "In addition, downregulation of ERAP1 protein expression (occurring in approximately 15% of cases) is associated with worse clinical outcome in cervical carcinoma patients." (PMID 26146606, 2015). "Importantly, we have previously shown that ERAP1 downregulation is significantly associated with decreased survival in cervical carcinoma." (PMID 26146606, 2015). "Moreover, two ERAP1 SNPs were found to be significantly associated with poor survival in Dutch cervical cancer patients." (PMID 25796583, 2015). "In the Javanese population, allele distributions at the ERAP1-127, ERAP1-528 and ERAP1-730 loci were significantly associated with altered cervical carcinoma risk (P = 0.042, 0.032 and 0.031, respectively); presence of the minor allele at these loci was associated with decreased cancer risk." (PMID 25796583, 2015). "As ERAP1 downregulation has been shown to be a significant predictor of decreased survival in cervical carcinoma, insight into the possible underlying mechanisms of this downregulation may yield novel targets for the designs of antitumor immunotherapies." (PMID 26146606, 2015). "The association between ERAP1 SNPs and cervical carcinoma risk or patient survival may be explained by different mechanisms, all related to altered ERAP1 function." (PMID 25566501, 2014). "Although defects in ERAP1 expression have been detected in various solid tumors, to date the only published report in which lower ERAP1 protein expression in neoplastic tissue was associated with worse survival, as well as the presence of metastases, is cervical carcinoma." (PMID 37101107, 2023). "The results indicated that, in ERAP1, the G allele of rs26653 may be associated with a lower risk of cervical cancer compared with C allele (OR = 0.829; 95% CI: 0.738–0.930) and the C allele of rs27044 may be a protective factor for cervical cancer (OR = 0.838, 95% CI: 0.746–0.941)." (PMID 32321463, 2020). "The SNP, rs26618, in ERAP1 leads to an amino acid substitution (I276M) and the current study showed that the CC genotype of this SNP may be associated with an increased risk of cervical cancer (OR = 1.53; 95% CI: 1.14–2.05) compared with TT-CT genotypes." (PMID 32321463, 2020). "In particular, while in Javanese a strong association between cervical carcinoma risk and ERAP1-575 locus on chromosome 5 and the TAP2-379 and TAP2-651 SNPs on chromosome 6 could be established, only the TAP2-651 locus correlated with carcinoma risk in Balineses." (PMID 32183384, 2020). "They identified a specific combination of four SNPs in genes encoding components of the APM (ERAP1-127, ERAP1-730, TAP2-651, and LMP7-145), which were associated with an increased cervical carcinoma risk." (PMID 32183384, 2020). "Six single nucleotide polymorphisms (SNPs) in ERAP1 and 5 SNPs in ERAP2 were selected and genotyped in 556 CIN patients, 1072 cervical cancer patients, and 1262 healthy control individuals." (PMID 32321463, 2020). "In the current study, we evaluated the influence of ERAP gene (ERAP1 and ERAP2) polymorphisms on susceptibility to cervical intraepithelial neoplasia (CIN) and cervical cancer." (PMID 32321463, 2020). "In cervical cancer, ERAP1 and ERAP2 proteins have been reported to be highly variable, ranging from low to high expression levels." (PMID 32321463, 2020). "The results showed that allelic and genotypic frequencies of rs26653 in ERAP1 were significantly different between cervical cancer and control groups (P = 0.001 and 0.004)." (PMID 32321463, 2020).
cervical carcinoma (continued). "The same authors, in a subsequent study investigated APM and HLA class I expression in 109 cervical carcinoma patients and for the first time reported a downregulation in ERAP1 expression in an HPV-derived cancerous lesion." (PMID 32183384, 2020). "Our results indicated that rs27044, rs26618 and rs26653 in ERAP1 and rs2287988 in ERAP2 influenced susceptibility to cervical cancer." (PMID 32321463, 2020). "Our findings suggest that these phenomena occur frequently in cervical carcinoma with ERAP1 downregulation." (PMID 26146606, 2015). "In conclusion, here we present the results of the first investigation of in vivo mechanisms of ERAP1 downregulation in cervical carcinoma." (PMID 26146606, 2015). "As shown, in the Javanese population, four ERAP1 SNPs and the TAP2-651 SNP were significantly associated with cervical carcinoma occurrence, whereas in the Balinese population, only the TAP2-651 locus showed this association." (PMID 25796583, 2015). "Eleven non-synonymous, coding SNPs in the TAP1, TAP2, LMP2, LMP7 and ERAP1 genes were genotyped in cervical carcinoma patients and healthy controls from two distinct Indonesian populations (Balinese and Javanese)." (PMID 25796583, 2015). "To address the issue of ERAP1 downregulation in cervical carcinoma, we have examined ERAP1 mRNA expression in tumor cells from a panel of cervical carcinoma lesions with known ERAP1 downregulation at the protein level." (PMID 26146606, 2015). "ERAP1 expression was also tested in 101 cervical carcinoma patients including adenocarcinomas and squamous cell carcinomas, and correlated with clinical outcome." (PMID 25566501, 2014). "Mehta and colleagues analyzed the effect of different ERAP1 SNPs and haplotype combinations on the risk of developing human papillomavirus (HPV)-induced cervical carcinoma." (PMID 25566501, 2014). "ERAP1 expression furthers the cancer progression, such as in cervical carcinoma." (PMID 36834865, 2023). "Specifically, in the Javanese population, a combination of the ERAP1-575 locus on chromosome 5 and the TAP2-379 and TAP2-651 markers on chromosome 6 was significantly associated with cervical carcinoma risk, whereas in the Balinese population, only the TAP2-651 locus exhibited this association." (PMID 25796583, 2015). "In the current study, we found that genetic polymorphisms in ERAP1 and ERAP2 genes might be associated with CIN and cervical cancer, and suggested that polymorphisms in key antigen-processing genes could affect susceptibility of cervical cancer." (PMID 32321463, 2020). "Although several studies have shown that various viral proteins, including the HPV E7 oncoprotein, can interfere with APM-related cellular processes (physically or at the transcriptional level), the mechanisms leading to ERAP1 downregulation in cervical carcinoma remain largely unknown." (PMID 26146606, 2015). "Therefore, rs27044 may play a role in cervical cancer by affecting ERAP1 function." (PMID 32321463, 2020). "The results showed that the ERAP1 haplotype, rs27044C-rs30187T-rs26618T-rs26653G-rs3734016C and the ERAP2 haplotypes, rs2549782T-rs2548538T-rs2248374G-rs2287988A-rs1056893T and rs2549782G-rs2548538A-rs2248374A-rs2287988G-rs1056893T may be associated with cervical cancer risk." (PMID 32321463, 2020). "The allelic frequencies of rs27044 in ERAP1 and rs2287988 in ERAP2 were significantly different between control and cervical cancer groups (P = 0.003 and 0.004)." (PMID 32321463, 2020). "Similarly, in cervical carcinoma induced by persistent infection and malignant transformation of the uterine cervical epithelium by human papillomavirus (HPV), increased cancer metastasis and decreased survival have been reported to be associated with several variants of ERAP1." (PMID 22942706, 2012). "Previous studies have identified potential marker genes (CSF1R, ERAP1, LDHA, etc.,) that may affect response rate by reshaping the cervical cancer microenvironment." (PMID 38206304, 2024).
cervical carcinoma (continued). "There were no SNPs in ERAP1 or ERAP2 that exhibited a significantly different distribution between the CIN and control groups or between the CIN and cervical cancer groups after Bonferroni correction (P > 0.0045)." (PMID 32321463, 2020).
Autoimmunity (12 papers, 2012 to 2025). The occurrence of an immune reaction against the organism's own cells or tissues. "ERAP1 is also polymorphic, and coding SNPs in the ERAP1 gene associate with predisposition to autoimmunity or cancer often in epistasis with HLA alleles and can help shape the cellular immunopeptidome." (PMID 34688668, 2021). "Overall, a very strong genetic link between ERAP1/2 SNPs and HLA-associated autoimmunity has been established and has contributed to our understanding of the pathogenesis of these diseases." (PMID 25566501, 2014). "Indeed, ERAP1 SNPs have been shown to both associate with HLA-dependent autoimmunity and cancer, often in epistasis with HLA, and to functionally affect the peptide products." (PMID 34688668, 2021). "Indeed, this aspect of ERAP1 function has been hypothesized as a pathogenetic mechanism in HLA-associated autoimmunity." (PMID 40189142, 2025). "Our results suggest highly significant mechanistic differences between the ancestral allotype 1 of ERAP1 with the autoimmunity-protective allotype 10." (PMID 39493758, 2024). "It has been suggested that an individual’s ERAP variant must generate autoantigenic peptides capable of stimulating pathogenic autoreactive T cells, in addition to the ratio of ERAP2 to ERAP1 favouring autoantigen processing for autoimmunity to occur." (PMID 38898675, 2024). "ERAP1 allotype 10 is highly protective toward developing some forms of autoimmunity and displays unusual functional properties, including very low activity versus some substrates." (PMID 39493758, 2024). "Recent genome-wide association studies have identified common variants of ERAP1 and ERAP2 linked to several human diseases, ranging from viral infections to autoimmunity and cancer." (PMID 22942706, 2012). "It is hypothesized that ERAP1 dysfunction compromises both innate and adaptive immune responses, thereby contributing to the onset and progression of autoimmune conditions." (PMID 40977735, 2025). "Thus, unravelling the mechanisms behind the functional properties of allotype 10 is crucial for a deep understanding of the role of ERAP1 in the development of autoimmunity as well as in adaptive immune response to cancer." (PMID 39493758, 2024). "Suboptimal antigens generated by altered ERAP1 and ERAP2 could trigger responses to commensal instead of pathogenic bacteria resulting in a chronically inflamed state or auto-antigen presentation resulting in autoimmunity." (PMID 41428259, 2025). "Of the 10 most common ERAP1 allotypes, allotype 10 (often referred to as Hap10) is a strong functional outlier that is found in approximately 22% of humans and has been reported to be protective for some forms of autoimmunity such as psoriasis and Behçet’s disease." (PMID 39493758, 2024). "The multitude of genetic and population studies linking ERAP1 and ERAP2 SNPs to pre-disposition to autoimmunity and viral infections prompted several research groups to examine the effects of the identified polymorphic variations on the enzyme’s biological function and molecular mechanism." (PMID 25566501, 2014). "This could imply that, in B*27:05 carriers, the same genetic allelic variants of ERAP1 and ERAP2 not predisposing to autoimmunity do not favour the presentation of uncanonical viral peptides as well." (PMID 37686141, 2023). "Interestingly, the pathogenesis of autoimmune/autoinflammatory disorders, such as AS, BD, BSCR and Ps, seems to arise, at least in part, by the epistatic interaction between ERAP1 and a HLA class I molecules (HLA-B*27, HLA-B*51, HLA-A*29:02 and HLA-C*06:02, respectively)." (PMID 33348540, 2020).
viral infections (11 papers, 2012 to 2025). "A possible explanation for this is that genetic variants of ERAP1 disturb the antigen-processing pathway, resulting in alterations in the immune dominance during viral infections." (PMID 36673116, 2023). "During viral infection, ERAP1 exerts a vital role in the establishment of immunity against specific epitopes." (PMID 39823241, 2025). "Single nucleotide polymorphisms (SNPs) in the endoplasmic reticulum aminopeptidase (ERAP1 and ERAP2) genes are associated with the pathogenesis of bacterial and viral infections." (PMID 33250919, 2020). "Previous findings in ERAP1‐KO mice indicate that ERAP1 downregulation influences the generation of numerous HCMV‐derived antigen peptides during viral infection, thus preventing recognition of viral antigens via CD8+ T cells during the process of host immunity." (PMID 39823241, 2025). "ERAP1-dependent trimming of epitope repertoire determines an efficacy of adoptive CD8+ T-cell responses in several viral diseases; however, its role in hepatitis B virus (HBV) infection remains unknown." (PMID 35602060, 2022). "It was discovered recently that the defective ERAP2 gene, not encoding functional aminopeptidase, may nevertheless, during viral infections, produce a truncated protein isoform of unknown function, possibly interfering with ERAP1 and full-length ERAP2 by heterodimer formation." (PMID 35769458, 2022). "In addition, the defective ERAP2 allele is not without function in immune defense as, in viral infections, it produces truncated protein isoform possibly interfering with ERAP1 and functional (allotype A) ERAP2." (PMID 35769458, 2022). "In addition, ERAP1 encodes an aminopeptidase important for processing of peptide fragments for MHC presentation, various SNPs in ERAP1 has been associated with infectious diseases, including viral infections." (PMID 34531865, 2021). "For example, CALR suppresses IFN-α production and antiviral activity in the context of hepatitis B virus infection, ERAP1 induces cleavage of cytokine receptors, and syndecan-4 (SDC4) negatively regulates retinoic acid-inducible gene I (RIG-I)-mediated signalling during virus infection." (PMID 35727847, 2022). "In addition, components of the antigen processing/presentation machinery that have so far obtained little attention, such as the endoplasmic reticulum aminopeptidase 1 (ERAP-1) might have a previously underestimated impact on immunodominance, as well as protection in viral infections." (PMID 32781731, 2020).
Hypertension (10 papers, 2012 to 2024). The presence of chronic increased pressure in the systemic arterial system. "Variants with low enzymatic levels of ERAP1 can elevate angiotensin levels, leading to vascular resistance and hypertension." (PMID 38534723, 2024). "They found various genetic variations of ERAP1 associated with incidental hypertension, a progressive increase in blood pressure, and essential hypertension." (PMID 38534723, 2024). "This ERAP1 deficiency decreases the conversion of Ang II to Ang IV, contributing to the hypertension observed in PE." (PMID 36848863, 2023). "The authors found three SNPs (ERAP1 rs469783 and rs10050860; ERAP2 rs2927615) to be associated with the risk of incident hypertension and one variant (ERAP1 rs27772) associated with blood pressure progression." (PMID 33567739, 2021). "Through a case/control cohort genetic study in Japanese population to interrogate previously known and also novel SNPs in ERAP1 gene, a significant association between the rs30187 SNP and hypertension was disclosed." (PMID 31223582, 2019). "In particular, an association between the ERAP1 rs30187 gene variant and hypertension was reported in a small cohort of 143 hypertensive and 348 normotensive Japanese subjects." (PMID 29850473, 2018). "Of note, the functional ERAP1 variant (rs30187) linked to AS, hypertension and HUS was associated with type 1 diabetes and multiple sclerosis." (PMID 22942706, 2012). "Hypertension and increased circulating Ang II levels are often associated with the enhanced generation of vascular reactive oxygen species (ROS), which are known to affect the ER redox potential and induce the release of ERAP1 into the bloodstream." (PMID 33567739, 2021). "Moreover, the ERAP1 rs30187 loss of function variant (K528R) was linked to the reduced degradation of Ang II and essential hypertension in a cohort of 143 hypertensive and 348 normotensive Japanese subjects." (PMID 33567739, 2021). "The ERAP1 rs30187 variant was also found to determine the degree of regression of left ventricular hypertrophy during anti-hypertensive treatment in patients with essential hypertension." (PMID 22942706, 2012). "ERAP2/Iso3, and also ERAP1 low activity allotypes, cannot perform these functions, thus moving equilibrium to stimulation of AT1R which causes vasoconstriction and hypertension." (PMID 35769458, 2022). "Zee and colleagues evaluated the potential association of 33 ERAP1 and 12 ERAP2 single nucleotide polymorphisms (SNPs) with blood pressure progression and incident hypertension in a cohort of 17,255 initially healthy White U.S. women." (PMID 33567739, 2021). "In another study, two other SNPs of the ERAP1 gene in the 3′UTR region, rs27980 and rs17086651, were associated with essential hypertension in a cohort of northeast Han Chinese patients." (PMID 33567739, 2021). "Multivariable Cox regression analysis showed an association of three tSNPs (ERAP1: rs469783 and rs10050860; ERAP2: rs2927615; all p < 0.05) with risk of incident hypertension." (PMID 29850473, 2018). "Results from the multivariable Cox regression analysis showed evidence for an association of three SNPs (ERAP1: rs469783 and rs10050860; ERAP2: rs2927615; all p-uncorrected <0.05) with risk of incident hypertension." (PMID 29850473, 2018). "(iii) Small case–control studies provided evidence that polymorphic variants of ERAP1 and ERAP2 are associated with preeclampsia and hypertension." (PMID 29850473, 2018). "The lower placental zinc may contribute to dysfunction of the ERp44/ERAP1 complex, exacerbating the hypertension in PE." (PMID 36848863, 2023). "(ii) Three ERAP1 and ERAP2 tSNPs are associated with risk of incident hypertension." (PMID 29850473, 2018). "The present study suggests that ERAP1 and ERAP2 gene variation may be useful for risk assessment of BP progression and the development of hypertension." (PMID 29850473, 2018).